INS (insulin)
Diseases named in the same sentence as INS in open-access papers (continued):
Sharing a sentence is not in itself a finding about the gene and the disease.
Insulin resistance (continued). "As C57BL/6J mice on a WTD are prone to develop adiposity-driven insulin resistance, we assessed insulin levels in the blood, which showed a trend toward a reduction upon immunoproteasomal inhibition." (PMID 38660806, 2024). "We reviewed the efficacy of using long-acting insulin analog, along with the infusion of regular insulin, in achieving glycemic control in patients with severe lactic acidosis and insulin resistance." (PMID 38365663, 2024). "In fact, the changes in insulin-related parameters, including less insulin resistance as indicated by the homeostasis model assessment of insulin resistance, were the only beneficial responses noted with the plant n6-PUFA diet." (PMID 38732558, 2024). "Homeostasis model assessment (HOMA) also evaluates insulin sensitivity, insulin resistance, and more." (PMID 38892625, 2024). "With rapid insulin resistance reversibility, we would recommend using only intravenous insulin and short acting subcutaneous insulin therapy and avoid longer acting subcutaneous insulin." (PMID 39588551, 2024). "In obese people, plasma free fatty acid levels are elevated, which leads to insulin resistance in the liver, endothelial cells, skeletal muscle, and other important insulin target organs." (PMID 38292473, 2024). "Chronic low-grade inflammation is a significant feature of T2DM patients, with elevated inflammatory markers disrupting insulin signaling and leading to insulin resistance." (PMID 39599721, 2024). "In this study, we used palmitate, a common dietary saturated free fatty acid known to induce insulin resistance, to establish an insulin-resistant cell model." (PMID 39095777, 2024). "In T2DM, the dysbiosis of gut microbiome promotes intestinal permeability, LPS translocation, hyperactivation of inflammatory responses and dysregulation of insulin‐related pathways, exacerbating the progression of insulin resistance." (PMID 38506069, 2024). "Insulin resistance (IR), a systemic disorder characterized by decreased sensitivity to insulin with an impaired ability to maintain normal glucose metabolism, has been implicated in various metabolic disorders." (PMID 38485964, 2024). "The extent of insulin resistance can be quantified using IR biomarkers like insulin levels, HOMA-IR index, and Triglyceride glucose–body mass index (TyG–BMI) levels." (PMID 39518747, 2024). "In a state of insulin resistance, adipose tissue becomes less sensitive to insulin, leading to increased lipolysis and the release of free fatty acids into the bloodstream, which in turn leads to increased triglyceride synthesis in the liver." (PMID 39229376, 2024). "Concerning the role of insulin resistance, we studied the effect of insulin levels on bone mineralization." (PMID 38163968, 2024). "This suggests that MK-2206 and AZD5363 inhibitors can induce insulin resistance by interfering with the insulin signaling pathway that regulates glucose metabolism." (PMID 39410536, 2024). "In insulin resistance states, the ability of skeletal muscle to take up glucose in response to insulin is markedly reduced." (PMID 39095777, 2024). "HOMA is a commonly used method for assessing islet function, including islet β cell function, insulin resistance and insulin sensitivity." (PMID 39737156, 2024). "In summary, berberine demonstrates significant potential as a natural compound for enhancing insulin sensitivity and addressing insulin resistance." (PMID 39407506, 2024). "The development of insulin resistance is formed by the complex effects of different metabolites affecting insulin signaling and inflammation." (PMID 39200098, 2024). "Adolescents with obesity and insulin resistance displayed elevated fasting glucagon levels and tAUC0-120 for glucagon, compared to insulin-sensitive individuals with obesity or normal weight." (PMID 39027470, 2024). "The inflammatory response can change the normal structure of β-cells, induce insulin resistance, and reduce insulin secretion." (PMID 38957396, 2024).
Insulin resistance (continued). "This highlights the importance of understanding the URL of blood insulin levels in adolescents to properly address pathological insulin resistance in this population." (PMID 38670169, 2024). "Insulin resistance is characterized by an insulin-mediated defect in glucose metabolism control, particularly in the muscles, adipose tissues, and liver." (PMID 38659573, 2024). "Specifically, NK-derived exosomes from lean mice were attenuated obesity-induced insulin resistance and inflammation in diabetic mice while enhancing insulin sensitivity and reducing inflammation in adipocytes and hepatocytes." (PMID 38455849, 2024). "Greater insulin resistance (i.e., lower insulin sensitivity) results in greater amounts of insulin being required to transport glucose into cells." (PMID 40604159, 2024). "It manifests through hyperglycaemia resulting from either target tissue insulin resistance, insufficient insulin production, or a combination of both." (PMID 39272460, 2024). "In the present study, we observed that fasting insulin, fasting glucose, and insulin resistance were significantly higher in obese PCOS patients than in lean PCOS patients." (PMID 38567220, 2024). "Results showed that 20-SLA reduced the impact of HFD on weight gain, normalized blood glucose and insulin levels, indicating that 20-HETE is related to obesity induced by hyperlipidemia and insulin resistance and impaired insulin signaling pathways." (PMID 39310267, 2024). "Insulin resistance (IR) is a condition of a diminished physiological response to normal insulin levels, that requires increased insulin production to maintain sufficient intracellular glucose concentrations." (PMID 38311745, 2024). "A clinical study analyzed the relationship between ΔPG and the characteristics of insulin resistance and insulin secretion in Chinese T2DM patients." (PMID 39839293, 2024). "Apart from the known decrease in insulin levels and insulin resistance, one of the most marked changes was observed for leptin, which decreased with both metformin or lifestyle intervention, with a further improved effect in the combined treatment arm." (PMID 38279016, 2024). "Previous studies in women with GDM did not perform cluster analysis, but performed subgroups, that were based on insulin resistance (Matsuda index or HOMA-IR) or on more complex insulin secretion measures (Stumvoll 1st phase index)." (PMID 39081793, 2024). "The reduction of insulin sensitivity is one of the determinants of obesity, and relations between insulin resistance and obesity are well known." (PMID 38255955, 2024). "Insulin resistance can stimulate EV release and alter the levels of insulin signaling proteins in EVs." (PMID 39735643, 2024). "Increased oxidative stress and inflammation can lead to insulin resistance, impaired insulin secretion, and, ultimately, T2DM." (PMID 39227562, 2024). "This can lead to difficulty in separating the true effect of insulin resistance from the effect of insulin secretion." (PMID 38805513, 2024). "Insulin resistance is a consequence of adipocyte hypertrophy from over storage of triglyceride as found in the system-level analysis of insulin action in multiple mouse strains." (PMID 39873003, 2024). "Over the past five years, numerous studies have highlighted vitamin D’s crucial role in both insulin secretion and insulin resistance." (PMID 39749014, 2024). "Levels of blood glucose, insulin and HOMA-IR confirmed the effectiveness of SG also from this point of view, improving insulin resistance, reducing the consequential risk of endothelial dysfunction, atherogenic lipid profile, and new hypertension onset." (PMID 38298437, 2024). "The antioxidant properties of SUA can help eliminate various substances, including singlet oxygen, peroxyl radicals, and hydroxyl radicals, thereby reducing metabolic inflammation, improving insulin resistance, and promoting insulin secretion." (PMID 38509610, 2024).
Insulin resistance (continued). "From these reviews, several crucial insights emerged, such as adipogenesis, lipid accumulation, insulin resistance/alteration of insulin sensitivity, inflammatory function, and gut microbiota dysbiosis." (PMID 38255955, 2024). "MFGE8 was a significant independent predictor of insulin resistance in this cohort on par with what we found for blood glucose, fasting glucose, and insulin levels." (PMID 38199575, 2024). "Enhanced expression of pro-inflammatory cytokines in obesity plays a role in inducing insulin resistance, the state characterised by impaired insulin-stimulated glucose uptake by myocytes and adipocytes, with reduced inhibition of liver glucose production." (PMID 38337640, 2024). "Elevated LPS levels activate inflammatory pathways that impair insulin signaling, contributing to insulin resistance and metabolic dysfunction." (PMID 39429422, 2024). "Due to insulin resistance or low amounts of secretion, insulin resistance or reduced secretion of insulin leads to elevated blood sugar levels." (PMID 39119415, 2024). "Associations of indicators of insulin resistance (HOMA-IR) and insulin sensitivity (Matsuda Index) with BMI percentile (BMIp) and age were assessed with adjustments for measures of insulin secretion, Index60 and insulinogenic index (IGI)." (PMID 37914981, 2024). "This biochemical disruption undermines insulin signaling pathways, contributing to insulin resistance—a critical factor in developing type 2 diabetes." (PMID 39796335, 2024). "Leptin-1 also increased serum adiponectin and decreased serum TNF-α and IL-6 level signifying the improvement in insulin-sensitivity and decrease in insulin-resistance, respectively in db/db mice." (PMID 39490585, 2024). "Of particular interest is the recently developed concept of brain insulin resistance, a condition characterized by altered insulin signaling in the central nervous system." (PMID 37721571, 2024). "Furthermore, several hypotheses, including insulin resistance, insulin deficiency, disrupted insulin signaling pathways, alterations in brain tissue architecture, changes in cerebral blood flow, immune dysregulation, and mitochondrial dysfunction, have been proposed." (PMID 39148536, 2024). "Insulin resistance denotes the condition where normal insulin levels fail to elicit downstream metabolism, resulting in reduced tissue sensitivity to typical insulin concentrations." (PMID 38615017, 2024). "It helps in the uptake of glucose in the cells through intracellular insulin uptake pathways, thereby increasing insulin sensitivity and decreasing insulin resistance which is the cornerstone in the development of various metabolic dysfunctions in PCOS." (PMID 38469011, 2024). "The oral disposition index has provided evidence of the critical role of insulin secretion for assessing insulin resistance and insulin sensitivity in validated populations." (PMID 37914981, 2024). "These cytokines have been identified as disrupting the insulin signaling process, resulting in insulin resistance and the onset of T2DM." (PMID 39328924, 2024). "Gestational diabetes mellitus is a critical condition that develops during pregnancy and is thought to be due to an increase in hPL, decreasing insulin sensitivity, and increasing insulin resistance." (PMID 38435884, 2024). "Insulin resistance is a condition whereby insulin-induced glucose uptake is impaired in the insulin sensitivity tissue." (PMID 39771030, 2024). "Excessive DXM injection increases insulin resistance with interference in glucose/insulin homeostasis and escalates liver lipid deposition." (PMID 39654538, 2024). "Insulin resistance (IR) is generally defined as reduced sensitivity to physiological insulin levels in insulin-targeting tissues." (PMID 38643148, 2024). "Insulin resistance, characterized by diminished insulin responsiveness and elevated blood glucose, exacerbates NAFPD pathology, creating a feedback loop." (PMID 39839297, 2024).
Insulin resistance (continued). "HOMA-IR is used to estimate insulin resistance and can be obtained using blood glucose and insulin concentrations." (PMID 39599757, 2024). "Our serum analysis data revealed a substantial increase (p < 0.0001) in HbA1c, glucose levels, insulin, and insulin resistance (HOMA-IR) in the AD model group (G4) in contrast to the control group (G1)." (PMID 39585487, 2024). "Insulin resistance, a condition that hampers insulin’s effectiveness in promoting glucose uptake in adipose and muscle tissues and reducing glucose production in the liver, can lead to the accumulation of inflammatory markers, including total leukocytes." (PMID 39604922, 2024). "Insulin resistance (IR) is characterized by a reduced response of insulin-sensitive organs and tissues to stimulation by insulin." (PMID 38397072, 2024). "Eventually, the patient was discovered to have Alström syndrome associated with insulin resistance and T2DM, which responded positively to insulin sensitizers, resulting in cessation of insulin." (PMID 39108603, 2024). "Free radicals generated within the body are partially implicated in the etiology of T2DM, as oxidative stress disrupts insulin-mediated intracellular signaling pathways, ultimately leading to insulin resistance in overweight individuals." (PMID 39275332, 2024). "The study can be improved by measuring serum insulin levels and applying a homeostatic model assessment for insulin resistance (HMOA-IR)." (PMID 39329045, 2024). "Simultaneously, insulin resistance down-regulates insulin signaling, preventing GLUT4 translocation to the cell surface, thereby reducing glucose uptake and usage." (PMID 39335666, 2024). "In the brain, insulin is crucial for neuronal survival, synaptic plasticity, and cognition; insulin resistance can impair insulin signaling pathways, leading to synaptic dysfunction, impaired neuronal metabolism, and cognitive decline." (PMID 39347125, 2024). "Obesity often coincides with insulin resistance, where cells become less responsive to the effects of insulin." (PMID 39118100, 2024). "Turkish pregnant women classified with night eating syndrome also presented greater HOMA-IR (Homeostasis model assessment of insulin resistance), insulin, total cholesterol, and high-density lipoprotein cholesterol." (PMID 39050138, 2024). "A recent meta-analysis has confirmed that adolescents aged 12–18 years with obesity are more likely to develop insulin resistance, and related indicators such as insulin, C-peptide, and HOMA-IR index were also elevated." (PMID 40302954, 2024). "Findings from this study suggest that insulin resistance and insulin sensitivity can be assessed using HOMA-IR and the Matsuda Index, respectively, in AAb+ relatives." (PMID 37914981, 2024). "Type 2 diabetes (T2D) is a complex metabolic disorder characterized by hyperglycemia resulting from impaired insulin secretion and/or insulin resistance." (PMID 39590846, 2024). "As the number of people with insulin resistance has increased, so too has research on the pathophysiology of insulin in the brain." (PMID 40604159, 2024). "FFAs activate PKC in the liver, thereby enhancing the exocytosis of insulin-resistant cells and opening chloride channels, which in turn intensifies insulin resistance." (PMID 39683601, 2024). "Insulin resistance of peripheral tissues, mainly muscle, reduces insulin-stimulated glucose uptake and postprandial hyperglycemia." (PMID 38672494, 2024). "The arising metabolic sequelae manifest as fasting hyperglycemia (> 100 mg/dL), hypertriglyceridemia (> 150 mg/dL), and impaired insulin signaling–features that describe the early onset of insulin-resistance." (PMID 39150916, 2024). "A study linked specific gut bacteria to increased branched-chain amino acids in insulin-resistant individuals, suggesting that dysbiosis can influence blood composition and contribute to insulin resistance." (PMID 39409832, 2024).
Insulin resistance (continued). "Obesity sets off a series of events that disrupt the normal pathways for insulin signaling, resulting in insulin resistance." (PMID 39310400, 2024). "TCAi and amino acids (AA) were measured at 0 min of a 75 g OGTT, while glucose, insulin, and FFA were obtained at 0, 30, 60, 90, 120, and 180 min to assess total area under the curve (tAUC180min) and insulin resistance (IR; tAUC180min of Glucose × Insulin)." (PMID 38561248, 2024). "Administration of betulin improved the glycemic response and decreased α–amylase activity in diabetic rats, although insulin levels and homeostatic model assessment for insulin resistance (HOMA–IR) scores remained unchanged." (PMID 38396842, 2024). "Insulin resistance is a metabolic condition in which the body’s cells become less responsive to the effects of insulin, a hormone crucial for regulating blood sugar levels." (PMID 39338165, 2024). "Type 2 diabetes (T2DM), characterized by insulin resistance and inadequate insulin production, presents a substantial public health challenge, necessitating comprehensive management strategies." (PMID 38978922, 2024). "The DAG theory suggests that DAG buildup in insulin-sensitive tissues leads to lipid-induced insulin resistance, which is caused by protein kinase C (PKC) interfering with insulin signaling." (PMID 39807459, 2024). "In contrast, blood glucose levels in the db/db group did not change significantly after insulin injection, indicating a marked decrease in insulin sensitivity and the presence of insulin resistance." (PMID 39712489, 2024). "In the presence of peripheral insulin resistance, i.e., decreased responsiveness to insulin-mediated glucose disposal or adipose tissue lipolysis, insulin concentrations increase and IGFBP-1 is suppressed." (PMID 39595651, 2024). "It’s generally believed that the pathophysiology of T2DM is rooted in impaired insulin responsiveness, known as insulin resistance (IR), coupled with inadequate insulin secretion." (PMID 39650653, 2024). "Insulin resistance is characterized by reduced cellular responsiveness to insulin, leading to impaired glucose uptake and metabolism, as much as it does in a normal population." (PMID 39469359, 2024). "This study posits PD-1+ CD4 Tconv cells as potential mediators of insulin resistance within insulin-sensitive tissues, substantiated by evidence from a diverse range of patient cohorts." (PMID 38380252, 2024). "We also calculated the HOMA-IR value, which is an index developed to evaluate the degree of insulin resistance from fasting insulin and glucose levels." (PMID 38999854, 2024). "Plasma glucose, serum insulin levels, and the homeostasis model assessment of insulin resistance (HOMA-IR) were determined as markers of peripheral IR." (PMID 39000130, 2024). "Insulin resistance can lead to increased levels of insulin and insulin-like growth factor 1 (IGF-1), which have been implicated in promoting the growth and proliferation of endometrial cells outside the uterus." (PMID 39199287, 2024). "Subjects with high GRS (≥ 0.836) had higher levels of glucose, insulin, homeostatic model assessment- insulin resistance (HOMA-IR), total cholesterol and triglycerides, and lower levels of arginine than subjects with low GRS (p < 0.05)." (PMID 38422035, 2024). "This disruption in insulin signaling impairs glucose uptake by cells, exacerbating insulin resistance." (PMID 39519193, 2024). "This activation further triggers the production of IL-1β and TNF-α, ultimately resulting in the impairment of insulin signaling and the development of insulin resistance (IR)." (PMID 39564209, 2024).